UFSP2 (UFM1 specific peptidase 2)
Description:
Thiol-dependent isopeptidase that specifically cleaves UFM1, a ubiquitin-like modifier protein, from conjugated proteins, such as CD274/PD-L1, CYB5R3, DDRGK1, MRE11, RPL26/uL24, TRIP4 and RPL26/uL24. While it is also able to mediate the processing of UFM1 precursors, a prerequisite for conjugation reactions, UFSP2 mainly acts as a protein deUFMylase that mediates deconjugation of UFM1 from target proteins. Mediates deUFMylation of RPL26/uL24, a critical step to release the UFM1 ribosome E3 ligase (UREL) complex during the recycling of 60S ribosome subunits from the endoplasmic reticulum. Catalyzes deUFMylation of TRIP4, regulating intracellular nuclear receptors transactivation and thereby regulate cell proliferation and differentiation.
Synonyms: C4orf20; FLJ11200; BHD; DEE106; SEMDDR
Tractability: PROTAC: ubiquitination databases record sites on it; its protein half-life has been measured.
Gene: Protein-coding gene on chromosome 4 (185,399,527 to 185,425,979, reverse strand). Ensembl gene ENSG00000109775.
Subcellular location: Endoplasmic reticulum; Cytoplasm; Nucleus
Subcellular location (Human Protein Atlas): Cytosol; Nucleoplasm
Gene Ontology:
Molecular function: deUFMylase activity; protein binding
Biological process: negative regulation of protein catabolic process; proteolysis; regulation of intracellular estrogen receptor signaling pathway; rescue of stalled ribosome; ribosome disassembly; regulation of type II interferon production
Cellular component: endoplasmic reticulum; cytoplasm; nucleus
Genetic constraint (gnomAD): Loss-of-function variants: 40 observed, 55.71 expected, observed/expected ratio (o/e) 0.72, 90% interval 0.56 to 0.94. The upper end of that interval is the gene's LOEUF score, 0.94, which puts it in group 3 of 6, group 1 being the genes least tolerant of losing a copy. Missense variants: 487 observed, 567.22 expected, observed/expected ratio (o/e) 0.86, 90% interval 0.8 to 0.93. Synonymous variants: 172 observed, 193.34 expected, observed/expected ratio (o/e) 0.89, 90% interval 0.79 to 1.01.
Homologues: Orthologues: chimpanzee UFSP2 (100% identical), macaque UFSP2 (98% identical), pig UFSP2 (95% identical), rabbit UFSP2 (94% identical), guinea pig UFSP2 (92% identical), dog UFSP2 (91% identical), mouse Ufsp2 (83% identical), rat Ufsp2 (83% identical), tropical clawed frog ufsp2 (65% identical), zebrafish ufsp2 (58% identical), Drosophila melanogaster Ufsp2 (39% identical), Caenorhabditis elegans odr-8 (37% identical). Paralogues in human: UFSP1 (17% identical).
Diseases named in the same sentence as UFSP2 in open-access papers:
UFSP2 is named in the same sentence as 27 diseases in open-access papers, as found by Europe PMC text mining. Sharing a sentence is not in itself a finding about the gene and the disease. The quoted sentences say what the papers report.
breast carcinoma (4 papers, 2015 to 2023). "In a study of colon cancer, depleting UfSP2 significantly promoted the growth of tumor cells, while UBA5 can be upregulated in breast cancer and associated with poor prognosis." (PMID 37947621, 2023). "More importantly, all the UFMylation system factors, including UBA5, UFC1, UFL1, UFM1, and UfSP2, were highly expressed in ERα-positive breast cancer cell lines and tissues." (PMID 37947621, 2023). "UFSP2 combined with the nuclear receptor coactivator ASC1 is involved in the development of breast cancer." (PMID 32513106, 2020). "Thus, each component of the UFM1-conjugating machinery and UFSP2 that reverses ufmylation process could be potential targets for development of drug against ERα-positive breast cancer." (PMID 25852645, 2015). "Moreover, UfSP2 depletion exacerbated ERα-mediated tumor formation; however, the expression of an ASC1-UFMylation-defective mutant or the depletion of UBA5 inhibited tumor growth, suggesting that the UFMylation of ASC1 is important for the transactivation of ERα and thus breast cancer development." (PMID 37947621, 2023).
epilepsy (4 papers, 2021 to 2025). A brain disorder characterized by episodes of abnormally increased neuronal discharge resulting in transient episodes of sensory or motor neurological dysfunction, or psychic dysfunction. "Exome sequencing of three patients with severe early-onset neurological disorders and epilepsy within a family revealed a homozygous mutation of c.344T > A (p.Val115Glu) in the UFSP2 gene, while their parents were heterozygous carriers." (PMID 39757643, 2025). "Different UFSP2 variants cause markedly different diseases, with homozygosity for V115E causing a severe syndrome of neurodevelopmental disability and epilepsy." (PMID 33473208, 2021). "The UFSP2 variants have also been implicated in epilepsy risk." (PMID 39757643, 2025). "Pathogenic variants in COL18A1, UFSP2, ZFYVE26, and ATP13A2 contribute to a wide range of clinical phenotypes, from ASM-resistant epilepsy and developmental delay to ataxia, intellectual disability, speech impediment, and other associated symptoms." (PMID 38783254, 2024). "Using WES, homozygous pathogenic variants in the COL18A1, UFSP2, ZFYVE26 and ATP13A2 genes were detected to cause ASM-resistant epilepsy and its comorbid conditions in four Pakistani families." (PMID 38783254, 2024).
colon cancer (2 papers, 2022 to 2024). "Moreover, UFSP2 mutation is frequently observed in colon cancer and uterine corpus endometrial carcinoma." (PMID 39247188, 2024). "By knocking down UFSP2 in colon cancer cell lines, there was an increase in the expression of key marker genes, including PCNA and MCM2 for DNA replication, CDK4 and CCND1 for cell cycle regulation, RPL26 for ribosome protein synthesis." (PMID 39247188, 2024). "Knockdown of UFSP2 expression was observed to significantly enhance the growth rates of colon cancer cells in vitro and in vivo." (PMID 39247188, 2024). "Human tissue microarrays further confirmed that levels of UFSP2 were significantly decreased in colon cancer patients." (PMID 35884562, 2022). "Additionally, an increase in total UFMylation levels was detected after UFSP2 depletion in cells and xenograft tumors, linking UFSP2 genomic alterations to the functional role of UFMylation in colon cancer." (PMID 39247188, 2024). "Knockdown of UFSP2 enhances the growth rates of colon cancer cells." (PMID 39247188, 2024). "The knockdown of UFSP2 promoted the growth of colon cancer cells and xenograft tumors." (PMID 35884562, 2022).
Beukes familial hip dysplasia (1 paper, 2014). "Recently, a mutation within the human UfSP2 has been identified to be associated with Beukes familial hip dysplasia, an autosomal dominant disorder characterized by premature degenerative osteoarthritis of the hip joint." (PMID 24921187, 2014). "A mutation in the UfSP2 gene could be determined as a cause of Beukes familial Hip Dysplasia (BHK)." (PMID 24921187, 2014).
frontotemporal dementia (1 paper, 2024). Frontotemporal dementia (FTD) comprises a group of neurodegenerative disorders, characterized by progressive changes in behavior, executive dysfunction and language impairment, as a result of degeneration of the medial prefrontal and frontoinsular cortices. "Futures studies should also analyze UFM1 and UFSP2 in non-tau neurodegenerative diseases such as frontotemporal dementia and Lewy body disease to test whether the UFMylation changes are specific for AD or for tauopathies in general." (PMID 39696466, 2024).
hepatocellular carcinoma (1 paper, 2025). A malignant tumor that arises from hepatocytes. "Moreover, O-GlcNAc of ZNF263 at Ser 662 promotes its chromatin association with OGT and facilitates its binding to the promoters of genes such as DOCK7, NPTX1, and UFSP2, thereby influencing hepatocellular carcinoma (HCC) progression." (PMID 41280891, 2025).
osteoporosis (1 paper, 2025). A condition of reduced bone mass, with decreased cortical thickness and a decrease in the number and size of the trabeculae of cancellous bone (but normal chemical composition), resulting in increased fracture incidence. "Interestingly, a strong negative correlation was found between UFSP2 and activated B cells (r = −0.82) and between CYB5R4 and effector memory CD8+ T cells (r = −0.86) in low-risk groups, implying that these cells may influence osteoporosis development through gene regulation." (PMID 40918403, 2025).
pancreatic cancer (1 paper, 2023). "Conversely, to test the participation of USFP2 in the modulation of cell proliferation and colony formation of the pancreatic cancer cells, UFSP2 was overexpressed in PANC-1 and Mia PaCa-2 cells, and cell growth-related characteristics were analyzed." (PMID 37280198, 2023). "Meanwhile, when UFSP2, the protease responsible for the cleavage of UFM1, was overexpressed, exactly same outcomes were observed in pancreatic cancer cells, which provides an additional line of evidence." (PMID 37280198, 2023). "In this study, the ufmylation of RPL10 was confirmed in the tissues of PAAD patients and pancreatic cancer cell lines, and this modification was mediated by UFL1 at specific sites and cleaved by UFSP2." (PMID 37280198, 2023).
cancer (8 papers, 2015 to 2024). A tumor composed of atypical neoplastic, often pleomorphic cells that invade other tissues. "Notably, UFSP2 copy number was heterozygous loss in cancer tissues and tumor cells, suggesting a possible haploinsufficiency of the UFSP2 gene." (PMID 39247188, 2024). "This is in contrast to cancer cells, where UFSP2 KO is known to enhance DNA damage response to counteract DNA damage." (PMID 38903110, 2024). "This is similar to cancer cells, where UFSP2 KO was shown to result in resistance towards DNA damage." (PMID 39696466, 2024). "Among the UFMylation genes, UfSP2 was frequently deleted in 14 cancer types." (PMID 37947621, 2023). "A comprehensive analysis of genomic alterations in the eight UFMylation family genes (UFM1, UBA5, UFC1, UFL1, UfBP1, CDK5RAP3, UfSP1, and UfSP2) across the TCGA database of 33 cancer types identified 55 recurrent and focal somatic copy number alteration events in UFMylation family genes." (PMID 37947621, 2023). "Amplification, deletion or mutation of genes encoding the UFMylation factors (UBA5, UFC1, UFL1, UfSP2 and UFM1) has been detected in malignant tumors from various tissues and organs in the TCGA database, indicating that UFMylation may promote or suppress tumorigenesis in different cellular contexts." (PMID 30783677, 2019).
tumor (4 papers, 2015 to 2024). "This pattern, along with high recurrent copy number loss, indicate that UFSP2 may perform tumor suppressive function." (PMID 39247188, 2024). "Previous research supports this assertion, showing that knockdown of UFSP2 enhances breast cancer cell growth and tumor formation." (PMID 39247188, 2024). "Specifically, ASC1 overexpression or reduced UfSP2 expression promotes tumor development, an effect mitigated by tamoxifen." (PMID 39247188, 2024). "An in vivo study found that ASC1 overexpression or UFSP2 depletion exacerbated ERα-mediated tumor formation, whereas tamoxifen treatment abrogated this effect." (PMID 35884562, 2022). "Remarkably, depletion of UFSP2 most dramatically promotes the cell growth and tumor formation, and this promotion can be abrogated by simultaneous depletion of ASC1, implicating the role of UFSP2 as a tumor suppressor." (PMID 25852645, 2015). "In addition, tamoxifen could completely reverse the stimulatory effects of ASC1 overexpression and UFSP2 depletion on colony formation and tumor growth." (PMID 25852645, 2015).
neurodevelopmental disorder (2 papers, 2021 to 2023). A behavioral and cognitive disorder with onset during the developmental period that involves impaired or aberrant development of intellectual, motor, or social functions. "Intriguingly, a variant of the deUFMylation enzyme Ufsp2 that enhances UFMylated protein levels was recently identified as a factor contributing to neurodevelopmental disorders in humans." (PMID 36917672, 2023). "UFSP2 variants are implicated in autosomal dominant skeletal dysplasias, but not neurodevelopmental disorders." (PMID 33473208, 2021).
neurological disorders (1 paper, 2021). "To obtain insights into UFSP2’s relevance to neurological disease, we examined the expression of UFSP2 and several UFMylation targets across mouse and human tissues." (PMID 33473208, 2021). "The structural and evolutionary analysis of UFSP2, its expression in the relevant tissues, and the lack of other shared, potentially disease-causing alleles among the families in the study, further support the variant’s pathogenicity in the neurologic disease observed in our patients." (PMID 33473208, 2021).
UFSP2 also shares sentences with these, for which no sentence is quoted: developmental delay (2 papers); Hip dysplasia (2); skeletal dysplasia (2); Anxiety (1); Ataxia (1); atherosclerosis (1); diabetes (1); Intellectual disability (1); ischemic heart diseases (1); Lewy body disease (1); neurodegenerative disease (1); schizophrenia (1); spondyloepimetaphyseal dysplasia (1); subarachnoid haemorrhage (1); tauopathies (1).